NCBP2L (nuclear cap binding protein subunit 2 like)
Synonyms: dJ820B18.1
Tractability: No criterion of Open Targets' tractability assessment is met for any kind of drug.
Gene: Protein-coding gene on chromosome X (107,774,899 to 107,795,829, forward strand). Ensembl gene ENSG00000170935.
Gene Ontology:
Molecular function: protein binding; nucleic acid binding; RNA binding; RNA cap binding
Biological process: mRNA cis splicing, via spliceosome
Cellular component: nuclear cap binding complex
Homologues: Orthologues: macaque NCBP2L (94% identical), pig NCBP2L (65% identical), tropical clawed frog ncbp2 (65% identical), dog NCBP2L (65% identical), zebrafish ncbp2 (63% identical), Drosophila melanogaster Cbp20 (58% identical), Caenorhabditis elegans ncbp-2 (50% identical). Paralogues in human: NCBP2 (67% identical).
Diseases named in the same sentence as NCBP2L in open-access papers:
NCBP2L is named in the same sentence as 3 diseases in open-access papers, as found by Europe PMC text mining. Sharing a sentence is not in itself a finding about the gene and the disease. The quoted sentences say what the papers report.
tumor (5 papers, 2022 to 2023). "The protein expressions of METTL1, NSUN2, EIF4G3, LARP1, NCBP1, and NCBP2 were higher in tumor tissues than in normal tissues; however, the protein expressions of WDR4, EIF4E1B, and NCBP2L were negative in both tumor and normal tissues." (PMID 35785179, 2022).
NCBP2L also shares sentences with these, for which no sentence is quoted: glioma (2 papers); cancer (1).